PRKDC (protein kinase, DNA-activated, catalytic subunit)
Diseases named in the same sentence as PRKDC in open-access papers (continued):
Sharing a sentence is not in itself a finding about the gene and the disease.
Renal insufficiency (1 paper, 2023). A reduction in the level of performance of the kidneys in areas of function comprising the concentration of urine, removal of wastes, the maintenance of electrolyte balance, homeostasis of blood pressure, and calcium metabolism. "It showed that aGVHD [HR = 5.66; 95% CI = [2.05, 16.73]; p < 0.001], infection [HR = 5.10; 95% CI = [1.85, 15.67]; p = 0.003] and PRKDC [HR = 4.44; 95% CI = [1.60, 13.68]; p < 0.006] were all independent risk factors for post‐transplant renal insufficiency." (PMID 37002788, 2023). "PRKDC, whose high expression was associated with post‐transplant renal insufficiency." (PMID 37002788, 2023).
thymoma (1 paper, 2021). A neoplasm arising from the epithelial cells of the thymus. "For example, PTK2 figured significantly in breast cancer (BRCA), three kidney cancer data sets [kidney chromophobe (KICH), kidney renal clear cell carcinoma (KIRC) and kidney renal papillary cell carcinoma (KIRP)], and thymoma (THYM), while PRKDC has distinct patterns in seven cancer studies." (PMID 34296749, 2021).
cancer (390 papers, 2000 to 2026). A tumor composed of atypical neoplastic, often pleomorphic cells that invade other tissues. "Recent study revealed that PRKDC mutation was corelated with high‐MSI status or high mutation load in cancers." (PMID 38898995, 2024). "Noteworthy, PRKDC is with 2.1% the sixth most frequently mutated DNA repair gene in all cancers and is identified as a candidate driver of hepatocarcinogenesis or therapy resistance, exhibiting frequent copy number gains." (PMID 37016451, 2023). "Previous studies have suggested that PRKDC participates in the regulation of transcription in various cancer cells, and our MS results indicated that PRKDC was closely associated with cccDNA." (PMID 35468873, 2022). "Mutation of the gene encoding DNA-PK protein PRKDC is associated with high mutation load or microsatellite instable (MSI)-high status in The Cancer Genome Atlas pan-cancer cohort." (PMID 36276148, 2022). "Genetic alterations of PRKDC, the gene encoding the catalytic subunit of DNA-PK, are common in several cancer types." (PMID 35008191, 2021). "The recognized effects and possible underlying mechanisms of PRKDC and DNA-PKcs in tumorigenesis and cancer development can be summarized from the following findings." (PMID 34702253, 2021). "PRKDC encodes DNA-PKcs protein that participates in the development of the immune system and is usually overexpressed in the cancer metastasis." (PMID 34236536, 2021). "We explored the prevalence of PRKDC mutations in the TCGA cohort and in the Geneplus cohort (a cohort of a Chinese pan‐cancer population)." (PMID 32502294, 2020). "To further explore the distinct phenotypic and immunologic states caused by PRKDC mutations, we performed GSEA with the Hallmark gene set in the PRKDC mutation group and the PRKDC wild‐type group based on the TCGA top 10 cancers dataset." (PMID 32502294, 2020). "When PRKDC mutations are present, cancer cells are resistant to apoptosis and there is an increase in the accumulation of DNA damage that promotes genome instability." (PMID 32502294, 2020). "Noteworthy, PRKDC is with 2.1% the sixth most frequently mutated DNA repair gene in all cancers and considered a potential oncogene, exhibiting frequent copy number gains." (PMID 31921645, 2019). "Downregulation of MYC mRNA and protein expression in multiple cancer cell lines is caused by inhibition of PRKDC, which leads to over-expression of MYC family of proteins induced DNA double-strand breaks and leads to cancer progression." (PMID 28871116, 2017). "PAPR1 inhibitors also show potential in many other cancers harboring deficiencies in DNA repair, and inhibition of other DNA repair genes is being evaluated to induce synthetic lethality, including PRKDC inhibition in MYC-overexpressing tumors." (PMID 27004405, 2016). "Aberrant expression or mutations of the PRKDC gene have been observed in various human cancers." (PMID 38732044, 2024). "The enhanced synergy of cancer cells harboring PRKDC mutation to the daunorubicin-EGFR inhibitor combination could result from inhibiting nonhomologous end joining-mediated DNA double-strand breaks repair." (PMID 37629110, 2023). "The proportion of TMB‐high in the PRKDC mutation group was 74% over a pan‐cancer analysis." (PMID 32502294, 2020). "We propose that checking for DNA-PK transcript or protein levels or the presence of mutations in PRKDC, alone or in combination with existing biomarkers, could improve the reliability of predictive indicators of a response to T cell–based cancer immunotherapies." (PMID 39436696, 2024). "Besides, 11 genes in the signature, such as coiled-coil domain containing 73 (CCDC73) and protein kinase, DNA-activated, and catalytic subunit (PRKDC), are proved to be prognosis marker genes or strongly associated with prognosis and progress of other types of cancer in published literature already." (PMID 32596394, 2020).
cancer (continued). "Studies have reported the association between PRKDC mutation and PDL1 expression in cancer, and evidenced the ability of PRKDC to be both the biomarker and drug target for checkpoint blockade therapy." (PMID 39323009, 2024). "Future investigations need to focus on the role of PRKDC in other cancer types and its interaction with various components of the immune system to further elucidate the therapeutic scope of targeting PRKDC." (PMID 39660143, 2024). "Over-expression of NHEJ factors (particularly Ku70 and PRKDC), however, occurred commonly in a broad spectrum of cancers." (PMID 38612901, 2024). "The results revealed a positive correlation between the expression level of PRKDC and the extent of copy number variations on chr8 in cancer cells (2.95 vs. 2.60, p = 0.031)." (PMID 38732044, 2024). "On the other side, data from TCGA database indicate that PRKDC genetic alterations are related with poor prognosis in several cancer cohorts and DNA‐PKcs is defined as a protumorigenic protein kinase to repair DSBs that cause resistance to treatment." (PMID 38898995, 2024). "In this study, for the first time, we conducted a pan-cancer analysis of PRKDC based on a variety of databases and online platforms to investigate the latent molecular processes of PRKDC in different tumor’s pathogenesis and clinical outcomes." (PMID 35801800, 2022). "In this study, we discovered that RIPK2 interacts with six protein kinases: MKK7 (MAP2K7), DNA-PKcs (PRKDC), RSK2 (RPS6KA3), MST4 (STK26), MEK2 (MAP2K2), and CSK (CSK), many of which were implicated in cancer metastasis." (PMID 35115556, 2022). "Inhibition of PRKDC leads to enhanced cytotoxicity of radiotherapy treatment and alkylating agents in cancer patients." (PMID 35054819, 2022). "For the first time, this research used numerous databases to perform a pan-cancer review for PRKDC to explore the possible mechanism of PRKDC in the etiology and outcomes in various tumors." (PMID 35801800, 2022). "This study revealed the potential value of PRKDC in tumor immunology and as a therapeutic target and prognostic biomarker in pan-cancer." (PMID 35801800, 2022). "PRKDC’s expression profile and prognostic significance in pan-cancer were investigated based on various databases and online platforms, including TIMER2, GEPIA2, cBioPortal, CPTAC, and SangerBox." (PMID 35801800, 2022). "PRKDC can drive cancer progression by interacting with androgen receptor or estrogen receptor to mediate transcriptional regulation." (PMID 35468873, 2022). "Concordantly, protein-protein interaction between PARP and PRKDC was predicted in the IPA network associated to cell death and survival, cell cycle, and cancer." (PMID 33656060, 2021). "Here, we discuss and review the structure and mechanism of action of PRKDC and DNA-PKcs and their relationship with cancer." (PMID 34702253, 2021). "Altered activities of NHEJ genes including XRCC5/KU80, XRCC6/KU70, PRKDC/DNA-PKcs, and TP53BP1 can be either negatively or positively associated with platinum resistance, depending on types of cancer cell lines or clinical samples." (PMID 34645978, 2021). "To further explore the association among PRKDC mutation, MSI status, and TMB, we included four clinical cohorts covering three cancer types." (PMID 32502294, 2020). "Our analysis of a pan-cancer cohort in the TCGA showed that solid tumors expressing high levels of PRKDC differ in the immune subtype from those with low PRKDC expression, on the basis of previously curated immune subtype models." (PMID 33207636, 2020). "PRKDC (also known as DNA-PKc) plays a critical role in ensuring genome integrity and in cancer in general by mediating ligation of double stranded breaks in DNA." (PMID 30681412, 2019). "Our decision to focus on PKRDC was furthermore fueled by the finding that the DNA-PKcs protein encoded by PRKDC has been shown to modulate cell survival, proliferation, invasion and migration in other cancers." (PMID 31382494, 2019).
cancer (continued). "To further test our findings in cancer cells, we investigated PRKDC suppression in a panel of human small-cell lung cancer (SCLC) cell lines with differential levels of MYC family gene amplification and mRNA expression." (PMID 25495526, 2014). "Briefly, cancer cells were stably infected with inducible TetOn lentiviruses where the expression of PRKDC shRNA was under the control of the doxycycline promoter." (PMID 25495526, 2014). "Together, our results suggest that the MYC oncogenic effect is dependent on PRKDC expression in multiple human cancers with high MYC expression levels." (PMID 25495526, 2014). "DNA-dependent protein kinase (DNA-PK), a gene product of PRKDC, is one of the proteins up-regulated in several metastatic and drug-resistant cancer cells." (PMID 23671674, 2013). "Several other phosphorylating substrates of PRKDC have also crucial role in cancer, like, c-Myc, PARP, c-JUN." (PMID 23437280, 2013). "Details of its expression in human cancer are controversial, so further studies will be needed to clarify the mechanism for PRKDC." (PMID 22559327, 2012). "DNA-dependent protein kinase (PRKDC) has been shown to modulate tumor sensitivity to chemotherapy and is a potential prognostic and predictive indicator of the efficacy of adjuvant chemotherapy in cancer patients." (PMID 39376611, 2024). "Notably, protein kinase, DNA-activated, catalytic subunit (PRKDC), and ubiquitin-specific protease 9X (USP9X) had higher mutation frequencies in multiple cancers, mainly including UCEC, SKCM, COAD, and STAD." (PMID 37540295, 2023). "This gives additional drug-repurposing insight, that the drug KU-60019, originally developed as a drug targeting ATM, could be used to target cancers with PRKDC LoF alteration." (PMID 37120674, 2023). "Therefore, we conducted a comprehensive study of PRKDC genes in 33 types of cancers based on TCGA, GTEx, and CPTAC databases, including gene expression, gene alteration, protein phosphorylation, TME, and biological pathways." (PMID 35801800, 2022). "Mutations of PIK3C2G, PRKDC and DMBT1 are also commonly found in cancer patients." (PMID 36038950, 2022). "We explored the prognosis value of PRKDC in pan-cancer base on several databases and platform." (PMID 35801800, 2022). "Additionally, previous studies have shown that high PRKDC/DNA-PK activity is likely used by cancer cells as a pro-survival pathway, leading eventually to resistance towards DNA damage-based therapeutic modalities." (PMID 35740268, 2022). "Here, we found that the lencRNA PRKDC-210 interacts with the CDK8 complex, resulting in transcriptional upregulation, which may be a major cause of abnormal gene expression in cancer." (PMID 36430260, 2022). "WGS data from the Pan-Cancer Analysis of Whole Genomes (PCAWG) dataset of 2,658 whole-cancer genomes across 38 tumour types found the most mutated DNA break repair mechanisms (DBRMs) genes to be FANCA, POLE, PRKDC and RAD51B." (PMID 36289474, 2022). "Therefore, the PRKDC gene contributes in the invasion of cancer cells by regulating secretion proteins." (PMID 34236536, 2021). "Conversely, STUMPs and LMSs shared 47 CNAs, in particular gain/amplification of the regions containing cancer related genes as PRKDC (8q11.21; eight samples), MLL3 (7q36.1; seven samples), ROCK2 (2p25.1; six samples), CTSB (8p23.1; six samples) and STAT2 (12q13.2; five samples)." (PMID 33557274, 2021). "When examined by CIBERSORT analysis through the TIMER2.0 web server, the mRNA levels of many DDR factors, such as RPA1, Ku70, Ku80, MRE11A, RAD50, NBS1, PRKDC, RAD51, PARG and XRCC4, were negatively associated with cytotoxic CD8+ T cells infiltration levels across various cancer types." (PMID 34970273, 2021). "High expression of PRKDC occurs in the majority of human cancers, compared to the matched normal tissue, which predicts dismal patient survival in the majority of TCGA cancer types." (PMID 33207636, 2020).
cancer (continued). "A recent study showed that PRKDC mutation was significantly associated with a high mutation load or high-MSI status in cancer on the basis of the TCGA pan-cancer cohort and, more importantly, PRKDC knockout and DNA-PKcs inhibitor enhanced the efficacy of immunological checkpoint inhibitors (ICI)." (PMID 33207636, 2020). "At the cellular level, MYC-induced γH2AX protein upregulation, a hallmark for DSB and replicative stress where PRKDC has an essential function, suggesting that MYC-driven cancer cells may be more dependent on DNA damage response components." (PMID 25495526, 2014). "Our results suggest that, mechanistically, the synthetic lethality observed between PRKDC suppression and MYC overexpression may in part be due to the reliance of MYC-expressing cancer cells on PRKDC-mediated DNA damage repair." (PMID 25495526, 2014). "We hypothesize that MYC-overexpressing cancer cells may become more reliant on the DNA damage repair machinery of PRKDC for survival." (PMID 25495526, 2014). "Thus, a possible scenario is cancer cells that are ‘addicted’ to MYC become highly sensitive to hindrance of PRKDC function, leading to subsequent interference of MYC transcription and protein translation and cancer cell death." (PMID 25495526, 2014). "Our study demonstrates that inhibition of PRKDC may offer a therapeutic strategy in MYC-driven cancers." (PMID 25495526, 2014). "Our data suggested synthetic lethality of PRKDC in MYC-overexpressing cancers." (PMID 25495526, 2014). "We hypothesized that since MYC-driven cancer cells may be more dependent on DNA damage pathways, PRKDC is an attractive candidate for a druggable synthetic lethal gene." (PMID 25495526, 2014). "On the individual gene level, PRKDC belonged to the NHEJ pathway, as the DDR gene with the most prevalent mutation (14.1% in pan-cancer) was one of the top 2 DDR genes ranked by mutation frequency in 10 kinds of cancers including COAD (23.68%), STAD (22.71%), LIHC (14.94%), and LUAD (14.49%)." (PMID 36081518, 2022). "Tumors with high level PRKDC are enriched with IFN‐γ‐dominant and wound healing subtypes, and significantly correlate with CD8+ T cell and B cell signatures across different cancer types." (PMID 38898995, 2024). "KRT80 has been observed to interact with PRKDC, activating the AKT signaling pathway and promoting cancer progression." (PMID 38495507, 2024). "In this analysis to discover cancer subgroups, PTDSS1, MCM4 and PRKDC genes were identified as molecular drivers belonging to the same subgroup." (PMID 37489460, 2023). "TAZ is a transcriptional coactivator upregulated in different types of cancer; its overexpression stimulates the expression of genes involved in NHEJ, such as TP53BP1 (53BP1), PRKDC (DNA-PKCs), and XRCC6 (Ku70), contributing to the radioresistant phenotype." (PMID 34900673, 2021). "Specifically, high PRKDC tumors were enriched with IFN (interferon)-γ-dominant and wound healing subtypes, and PRKDC expression significantly correlates CD8+ T cell and B cell signatures across different cancer types." (PMID 33207636, 2020). "Specifically, EGFR is a widely studied oncogene with a potential role in cancer therapeutics, six are core genes (AURKA, CDK1, CDT1, PRKDC, RAD51, and XRCC2), six are potential drug targets, and five were identified as drug actionable genes." (PMID 33240468, 2020). "The most frequently amplified genes across the Pan-Cancer Atlas were NBN (n = 4,275, 40.8%), EXO1 (n = 3,714, 35.4%), PARP1 (n = 3,695, 35.2%), PRKDC (n = 3,650, 34.8%) and POLB (n = 2,794, 26.6%)." (PMID 32226530, 2020).
cancer (continued). "Collectively, these data indicate that PRKDC modulates c-MYC mRNA and protein expression in these cancer cell lines; the effect on MYC protein abundance is at least in part through reduction of MYC mRNA." (PMID 25495526, 2014). "At the molecular level, we found that inhibition of PRKDC downregulated MYC mRNA and protein expression in multiple cancer cell lines." (PMID 25495526, 2014). "There was no publication with PRKDC pan-cancer analysis from a holistic oncology approach, according to a literature search." (PMID 35801800, 2022). "This gene and its binding partner PRKDC promote non-homologous end joining (NHEJ) in cancer cells resulting in chemoresistance in head and neck malignancies where inhibitors of NHEJ, such as Nu7026, are believed to re-sensitize cells to cisplatin." (PMID 26680454, 2015). "Our hypothesis is that in cancer cells, MYC overexpression induces DSBs and PRKDC plays a pivotal function in repairing this DNA damage, leading to cancer cell survival." (PMID 25495526, 2014). "While protein kinase, DNA-activated, catalytic subunit (PRKDC) plays an important role in double-strand break repair to retain genomic stability, there is still no pan-cancer analysis based on large clinical information on the relationship between PRKDC and different tumors." (PMID 35801800, 2022). "We are the first to comprehensively describe that PRKDC mutations, regardless of the status of other DDR‐related genes, and found an association with an increased TMB, an increased mRNA expression of immune‐related genes, and a superior response to ICI in pan‐cancer patients." (PMID 32502294, 2020). "However, despite the links between LMNA and DNA-PK/PRKDC and DNA-PK and DDR, no report has investigated their relationship or its role in chemoresistance in GBM or cancer." (PMID 41271669, 2025).